INS (insulin)
Diseases named in the same sentence as INS in open-access papers (continued):
Sharing a sentence is not in itself a finding about the gene and the disease.
Hepatic steatosis (continued). "We examined the effects of chronic dietary NDGA treatment on hypertriglyceridemia and hepatic steatosis, and profiled by microarray analysis the expression of enzymes and regulatory proteins involved in lipid metabolism of three insulin-sensitive tissues liver, skeletal muscle and adipose tissue." (PMID 27708683, 2016). "In ob/ob mice, this lipid ameliorates insulin sensitivity and hepatic steatosis." (PMID 27548138, 2016). "In a cross-over study which forms the pilot data for this trial, patients in the MedDiet arm had significant improvements in insulin sensitivity as determined by a 3-hour hyperinsulinaemic-euglycaemic clamp and a significant reduction (39 %) in hepatic steatosis." (PMID 26831892, 2016). "More specifically exercise has been shown to be effective at modulating hepatic steatosis and its mediators, improve body composition, liver and adipose tissue insulin sensitivity independent of weight loss." (PMID 27023533, 2016). "Experimental models in animals and adults have shown that long chain ω-3 fatty acids, known important regulators of hepatic gene transcription, can decrease hepatic steatosis, improve insulin sensitivity and cardiovascular disease and decrease markers of inflammation." (PMID 27314342, 2016). "Collectively, reductions in oxidative stress and ceramide biosynthesis may play an important role in the improvement of hepatic steatosis and insulin sensitivity in DIO mice supplemented with ChrSd." (PMID 27977712, 2016). "DDP-IV inhibitors improve insulin sensitivity and hepatic steatosis in animal models of diet-induced obesity with some evidence of improved liver inflammation and may also limit progression to fibrosis in animal models of liver injury." (PMID 26856933, 2016). "Subcapsular hepatic steatosis is a rare atypical pattern of fatty deposition of the liver reported in patients with diabetic nephropathy receiving peritoneal dialysis with intraperitoneal insulin." (PMID 27998312, 2016). "Conversely, oral administration of DEFA5 suppressed ileal H. hepaticus and prevented endotoxemia, systemic inflammation and hepatic steatosis in the HFD+VDD mice, revealing a causal role of alpha-defensins in attenuating biogenesis of systemic inflammation, insulin resistance, and hepatic steatosis." (PMID 27895587, 2016). "It seems that insulin plays a crucial role in pathology of fatty liver disease." (PMID 28224024, 2016). "Given that increased ALT is a frequent marker of fatty liver disease, our finding of significant association between ALT and insulin clearance also supports this hypothesis." (PMID 27846285, 2016). "It seems that pathways related to insulin have a prominent role in fatty liver disease." (PMID 28224024, 2016). "Our metabolic measurements indicated that oral gavage of HFrD fed rats with NDGA significantly decreased plasma glucose, fatty acids, TG and insulin levels nearly to levels observed in chow fed control, and attenuated hepatic steatosis as assessed by determination of liver TG content." (PMID 26394137, 2015). "In addition to berberine enhancing insulin sensitivity, this compound reduces hyperlipidemia and ameliorates fatty liver." (PMID 26228038, 2015). "In the NAFLD “portal theory,” there is an exacerbated release of FFAs, endotoxins, and proinflammatory cytokines of visceral fat that reach the liver, via portal system, promoting the development of liver resistance to insulin, hepatic steatosis, and inflammation in obese individuals." (PMID 26120587, 2015). "Therefore, potential systemic alteration (e.g., plasma levels of free fatty acid, TG, glucose and insulin) and other metabolic factors (e.g., body composition, adiponection) involved in hepatic steatosis should be investigated." (PMID 26608583, 2015). "Interestingly, Apoe−/− mice are also characterized by enhanced hepatic steatosis as well as improved insulin sensitivity." (PMID 26695075, 2015).
Hepatic steatosis (continued). "Most other types of lipodystrophies may have the similar mechanisms for the development of hepatic steatosis, such as increased de novo lipogenesis, insulin resistance and reduced β-oxidation." (PMID 26690553, 2015). "Several studies have shown that high-fructose intake may lead to adverse metabolic alteration, in particular increase in plasma TG, hepatic insulin resistance, and liver steatosis." (PMID 26090419, 2015). "In fact, many genes implicated in hepatic steatosis are not related to insulin signalling, including FABPs." (PMID 26052340, 2015). "Fasting plasma glucose, lipids/lipoproteins, insulin and leptin levels were quantified, histopathologic score of hepatic steatosis and inflammation were assessed, and the responses of common checkpoints of insulin and leptin signalling responsible for lipogenesis and gluconeogenesis were analyzed." (PMID 25658428, 2015). "In addition to adipose tissue dysfunction, recent studies have implicated increased intramyocellular lipid content, increased muscle insulin resistance and impaired skeletal muscle energy metabolism in hepatic steatosis." (PMID 26439744, 2015). "Interestingly, JNK-1 deficiency in adipose tissue protects against hepatic steatosis and promotes glucose intolerance, insulin clearance, IR, and hepatic steatosis." (PMID 26136779, 2015). "These improvements also lead to reduced hepatic steatosis and enhanced hepatic insulin sensitivity." (PMID 26243466, 2015). "Recent data also suggest that berberine could also induce improvement in liver steatosis, probably as consequence of the relevant changes induced in triglycerides level and insulin-sensitivity." (PMID 25886384, 2015). "The aim of the current study is to determine the temporal relationships between the development of hepatic steatosis and the onset of insulin and leptin resistance in hypothalamus and liver in male Wistar rats (six weeks of age) fed chow or HFHS diet for up to 8 weeks." (PMID 25658428, 2015). "This may be due to the increased inflammatory cytokines, insulin resistance, and free fatty acid promoted by the expanded and inflamed visceral fat mass in patients with fatty liver." (PMID 25781622, 2015). "Despite notably decreasing hepatic steatosis, GC-1 increased serum insulin levels over 5-fold." (PMID 25849936, 2015). "As a result, the weight loss was not different between the two types of diet; there was a significant reduction in relative hepatic steatosis after the Mediterranean diet compared to control diet, with improved insulin sensitivity being observed only with the Mediterranean diet." (PMID 26512643, 2015). "Similarly, adenovirus-mediated short-term GRP78 over-expression reduced hepatic steatosis and improved insulin sensitivity in db/db mice." (PMID 24465394, 2014). "Thus, improving hepatic insulin sensitivity probably due to reduced hepatic steatosis should be important in preventive strategies." (PMID 25097861, 2014). "Leptin may contribute toenhance hepatic steatosis by changing actions of insulin on tissues and its receptors, and it may influence the development of NASH through the regulation of inflammatory responses." (PMID 24829591, 2014). "Globular adiponectin may ameliorate the hepatic steatosis by stimulating insulin secretion and improving glycolipid metabolism in skeletal muscle." (PMID 24683323, 2014). "The beneficial metabolic effects of Compound B may, at least partly, be ascribed to suppressed fat absorption from the intestine via inhibited intestinal DGAT1, as postprandial hyperlipidemia is assumed to promote hepatic steatosis and insulin resistance." (PMID 25405858, 2014). "In additional to conventionally thought of antioxidants, part of the ability of metformin to improve insulin sensitivity and reduce hepatic steatosis may be due to decreased mitochondrial ROS production." (PMID 25371775, 2014).
Hepatic steatosis (continued). "However, further studies are necessary to elucidate chemerin influence on insulin sensitivity and hepatic steatosis in CHC." (PMID 25121101, 2014). "Globular adiponectin could ameliorate the hepatic steatosis and vary the expressions of adiponectin receptors in liver and skeletal muscle by stimulating insulin secretion." (PMID 24683323, 2014). "This review highlights the intricate relationship between redox-sensitive proteins and insulin signalling in the context of fatty liver disease, and to a larger extent, the importance of reactive oxygen species as primary signalling molecules in metabolically active cells." (PMID 24672550, 2014). "It is still not clear whether increased ROS is a major player in decreased insulin signalling in fatty liver disease." (PMID 24672550, 2014). "Our findings are two-fold and relate to hepatic steatosis and insulin sensitivity." (PMID 23837919, 2013). "The findings of our study relate to hepatic steatosis and insulin sensitivity." (PMID 23837919, 2013). "In addition to their control of lipid metabolism, several of these lipogenic genes, including Cidea, Cidec, and Cd36, play a critical role in regulating the development of hepatic steatosis and insulin sensitivity." (PMID 23505504, 2013). "This study suggests that the favorable effects of a BM extract on increasing insulin sensitivity and attenuating hepatic steatosis may be mediated by enhanced FGF21 and AMPK-Sirt1 signaling." (PMID 24189525, 2013). "In contrast, adoptive transfer of iNKT or in vivo activation of iNKT via the lipid ligand α-galacotcylceramide, decreased fat accumulation, triglyceride and leptin (a pro-inflammatory adipokine) levels, liver steatosis and improved insulin sensitivity via anti-inflammatory cytokine production." (PMID 24084730, 2013). "Similarly, GRP78 overexpression has beneficial metabolic effects, including reducing liver steatosis and increasing insulin sensitivity in the liver in obese mice." (PMID 23762873, 2013). "Importantly, GLP-1 receptors are present in human hepatocytes and their activation produces a direct effect on hepatic steatosis, increasing hepatic insulin signaling and sensitivity." (PMID 24264040, 2013). "The initial “two hits” hypothesis described insulin resistance as “first hit” that leads to hepatic steatosis and is followed by a “second hit” driven by oxidative stress, which in turn leads to the development of steatohepatitis and fibrosis." (PMID 24084730, 2013). "In fact subjects with either mutation for PNPLA3 gene, familial hypobetalipoproteinemia or mutation in DGAT, have fatty liver but peripheral and hepatic insulin sensitivity comparable to matched subjects without mutation and NAFLD." (PMID 23666091, 2013). "Also, there was a significant relationship between OSI and insulin sensitivity in obese adolescents with fatty liver." (PMID 23367495, 2013). "Hepatic steatosis is another marker that reflects liver insulin sensitivity." (PMID 23139832, 2012). "Importantly, only the phospholipid form reduced plasma insulin and adipocyte hypertrophy, while being more effective in reducing hepatic steatosis and low-grade inflammation of WAT." (PMID 22701720, 2012). "Interestingly, the STZ injected T1FLD mice had hepatic steatosis but with low circulating plasma insulin levels they had a reduced liver pAkt to total Akt ratio." (PMID 22745692, 2012). "For this reason, hepatic steatosis may be a cost of improved insulin sensitivity at both systemic and hepatic levels." (PMID 22768070, 2012).
Hepatic steatosis (continued). "This PTP1B inhibitory property may represent a promising role for curcumin to treat fructose-induced hepatic steatosis induced by hepatic insulin and leptin resistance." (PMID 22991573, 2012). "These mice are obese, insulin resistant and have hepatic steatosis." (PMID 22966224, 2012). "In obese subjects there is also an increased flux of free fatty acids to the liver due to their excessive accumulation in the adipose tissue and to the inability of insulin to suppress lipolysis in adipocytes due to insulin resistance, which leads to steatosis or fatty liver disease." (PMID 22844426, 2012). "The vast majority of children with fatty liver disease are found to be obese and insulin resistant." (PMID 22224077, 2011). "Additionally, some insulin resistant animals showed changes in cell morphology including ballooning, a feature of progressing fatty liver disease." (PMID 22125617, 2011). "Chronic exogenous GH has preventive effects against hepatic steatosis and fatty liver, and may be realized through reduced fat weight, enhanced insulin sensitivity and correction of oxidative stress." (PMID 20653983, 2010). "In hepatic steatosis it is believed that mitochondrial dysfunction and decreased fatty acid β-oxidation are precipitating causes for increased intracellular FFA accumulation and hepatic insulin resistance." (PMID 20300478, 2009). "Anti-inflammatory effects of pharmacotherapy, such as insulin sensitizers, might play a role in the reduction of fatty liver and steatohepatitis severity." (PMID 16707022, 2006). "The results suggest that in routine fatty liver screening and diagnosis, clinical sonographers could incorporate patients’ serum insulin levels as an auxiliary reference marker to facilitate earlier metabolic risk assessment and intervention for individuals with suspicious imaging findings." (PMID 41560026, 2026). "Furthermore, the absence of pivotal measurements, such as insulin and hepatic steatosis, limits the ability to elucidate the mechanisms underlying the observed improvement in glycemic control." (PMID 41233363, 2025). "While the improvement in VLDL and TG clearance observed in control subjects might be considered a classic effect of exercise training in overweight individuals, the responses of PLWH have likely revolved around the improvement in insulin sensitivity and hepatic steatosis." (PMID 41590624, 2025). "Gut-derived SCFAs promote insulin sensitivity, reduce adiposity and body weight and downregulate PPARα, increasing oxidative metabolism in the liver and adipose tissue and thus lowering fat accumulation, and hepatic steatosis and increasing insulin sensitivity." (PMID 40696355, 2025). "Similarly, DCI supplementation in rats reduced body weight and circulating triglyceride, cholesterol, insulin and fasting glucose levels, while also improving hepatic steatosis, which the authors attributed to activation of the Adiponectin/AMPK/PPAR transcriptional axis in the liver." (PMID 41032702, 2025). "Preclinical studies suggest that tirzepatide, a dual GLP-1/gastric inhibitory polypeptide receptor agonist may offer superior metabolic benefits compared to conventional GLP-1 agonists by improving β-cell function, enhancing insulin sensitivity, and reducing fatty liver progression." (PMID 40430489, 2025). "Future research should focus on identifying strategies to enhance adherence to the MD in the pediatric population, as increasing evidence suggests that, even without weight loss, the MD reduces liver steatosis and improves insulin sensitivity in insulin-resistant adults with MASLD." (PMID 41515146, 2025). "Similarly, 6-gingerol has shown robust activity in metabolic disease models: it improved insulin sensitivity, reduced hepatic steatosis and lipid accumulation, and alleviated inflammation and oxidative stress in high-fat diet-fed mice and palmitate-treated HepG2 cells." (PMID 40577283, 2025).
Hepatic steatosis (continued). "Emerging evidence suggests that these agents may also confer hepatoprotective effects through multiple mechanisms including reduction of hepatic steatosis and fibrosis, improvement in insulin sensitivity, anti‐inflammatory actions, and modulation of the gut‐liver axis." (PMID 41388641, 2025). "Additionally, research focused on the mechanisms behind the beneficial effects of these interventions—such as their impact on hepatic steatosis, inflammation, insulin resistance, and gut microbiota composition—will provide deeper insights into the role of nutrition in managing MASLD." (PMID 40219014, 2025). "Furthermore, Impaired cellular glucose uptake response to insulin, plus an excess influx glucose uptake response increased lipolysis of white adipose tissue, compounded by increased rates of hepatic denovo lipogenesis, leads to hepatic steatosis." (PMID 39610482, 2024). "The underlying mechanisms of the negative association between blood Cr and hepatic steatosis may involves the alterations in insulin sensitivity, immunity, oxidative stress, gluco-lipid metabolism and gut microbiota by Cr." (PMID 38721033, 2024). "These foods improve insulin sensitivity, while components such as monounsaturated fats and polyphenols have anti-inflammatory and antioxidant actions, thus contributing to the reduction in hepatic steatosis and inflammation, as also observed in the results of our study." (PMID 39683618, 2024). "Interestingly, in a study of obese mice, apelin treatment resulted in decreased hepatic steatosis by reducing de novo lipogenesis, although this may be an indirect effect due to the increase in insulin sensitivity." (PMID 39519480, 2024). "Moreover, piperine supplementation at a dose of 50 mg/kg body weight to male C57BL/6N mice with high-fat diet-induced hepatic steatosis, resulted in a significant increase in plasma adiponectin levels, together with reduced insulin, blood glucose and hepatic lipid levels." (PMID 37047589, 2023). "In addition to the optimised intake of dietary fibre, sustained weight loss represents an extremely effective therapy for MAFLD, with the demonstration of reversal of hepatic steatosis and improved hepatic insulin sensitivity and glycaemic control following moderate weight reduction of T2D." (PMID 37367914, 2023). "Consequently, CTRP9 knockout mice display decreased insulin sensitivity and hepatic steatosis." (PMID 36831095, 2023). "It has been shown that healthy fatty acids (MUFAs and PUFAs [particularly omega‐3 FAs]) could prevent NAFLD by reducing triglycerides, glucose, oxidative stress, and hepatic steatosis as well as improving insulin sensitivity, anti‐inflammatory effect, and inhibiting hepatic fat accumulation." (PMID 37823171, 2023). "Notably, considering the pivotal role of PPARγ in governing glucose and lipid metabolism, our finding that ufmylation on UFBP1 downregulated PPARγ expression may decipher the phenotypic alterations in hepatic steatosis, serum lipids and insulin sensitivity." (PMID 37660122, 2023). "Furthermore, ANGPTL4 improved glucose tolerance and IR by downregulating insulin signaling pathway-associated genes, such as Akt, Janus kinase 2/signal transducer and activator of transcription-3 (JAK2/STAT3), but promoted diet-induced hepatic steatosis." (PMID 37180779, 2023). "Furthermore, hepatic steatosis (independent of adiposity), is associated with impaired insulin action within the liver, but also within the periphery (including adipose tissue and skeletal muscle), in both lean and non-diabetic obese people." (PMID 37367914, 2023). "Our findings may indicate a novel link between Sar1b-mediated lipid absorption and metabolism, which is supported by our previous work pointing out that transgenic mice overexpressing Sar1b developed a rise in body weight, adiposity, hepatic steatosis, plasma lipids and insulin insensitivity." (PMID 37558128, 2023).